PLCG1 (phospholipase C gamma 1)
Diseases named in the same sentence as PLCG1 in open-access papers (continued):
Sharing a sentence is not in itself a finding about the gene and the disease.
infection (20 papers, 2008 to 2025). The state of being infected such as from the introduction of a foreign agent such as serum, vaccine, antigenic substance or organism. "This ‘targeting’ of PLCG1 by Salmonella seems to be a feature of infection between 24-96 hours post-infection." (PMID 35846741, 2022). "PLCG1 would be a logical focal point of the initial Salmonella colonization/infection repertoire since it is involved in regulating innate immune functions including phagocytosis, the oxidative burst, cell migration and TLR-mediated signaling." (PMID 35846741, 2022). "This approach can also be used for the in silico identification of new targets against pathogen infection, as demonstrated here by the identification of PLCγ1 as a target for ERK1/2 deactivation." (PMID 18194572, 2008). "In NAc homogenates, enrichment analyses identified pathways related to immune modulatory pathways, including various types of infection (e.g., KRT14,16,17; HLA-B) and leukocyte migration (e.g., JAM2; PLCG1)." (PMID 37674018, 2023). "Upon ectopic expression, K15 has been shown to activate the PLCγ1-calcineurin-NFAT, MAP-Kinase as well as the NF-κB pathways, which are crucial both during KSHV primary infection as well as during its reactivation from latency (see Introduction)." (PMID 28938025, 2017). "Infection with wt EBOV resulted in the increase in phosphorylation of Lck; however, phosphorylation of additional adapters including ZAP70, PLCγ1 and SLP76 appeared to be blocked." (PMID 27930745, 2016). "Silencing of PDPK1, Akt1 and PLCγ1 resulted in significant reduction of VSV-S but not VSV-G infection." (PMID 36245045, 2022). "Secondly, phospholipase C-1 (PLCG1) and calmodulin were significantly dephosphorylated in the S. Enteritidis-infected cecal tissue by 4 hours post-infection when compared to the non-infected control cecal tissue." (PMID 35846741, 2022). "Unexpectedly, infection with EBOV/VP24m resulted in an increase in the relative amount of phosphorylated ZAP70 despite the lack of phosphorylation of the downstream signaling molecules PLCγ1 and SLP76; however, this is consistent with the lack of effective T cell activation by this mutant." (PMID 27930745, 2016). "Lastly, since excessive inflammatory reaction post-TMEV infection is a major driver for the development of seizures in this model (Löscher and Howe, 2022), it is likely that inhibiting BDNF signaling mediated through PLCγ1 alone may not have significant anticonvulsant effects." (PMID 35874836, 2022).
brain disorder (5 papers, 2019 to 2024). A disease affecting the brain or part of the brain. "Prior studies have reported the potential role of PLCG1 in both normal brain function and brain disorders, including MDD." (PMID 34859065, 2021). "Consistent with its critical role, abnormal expression and activation of PLCγ1 has been observed in various brain disorders." (PMID 31114483, 2019).
hematologic cancers (2 papers, 2022 to 2024). "Furthermore, we found that expression levels of ZAP70, FYN, GRAP2, ITK, and LCK as well as two further TCR pathway kinases, PLCG1 and LAT, were highest in human T-ALL cell lines compared with other hematopoietic cancer lines." (PMID 38618957, 2024).
blood cancer (1 paper, 2025). "In this study, we used two commonly used blood cancer cell lines Jurkat and Hut78 to investigate PLCG1 signaling." (PMID 40796680, 2025).
PLCG1 also shares sentences with these, for which no sentence is quoted: immune disorders (9 papers); autoimmune disease (3); Autoimmunity (3); meningioma (3); small cell lung carcinoma (3); T-cell leukemia (3); atherosclerosis (2); bipolar disorder (2); chronic lymphocytic leukaemia (2); digestive system tumors (2); hematologic malignancies (2); Huntington disease (2); memory impairment (2); Obesity (2); Stroke (2); Acidosis (1); acute leukemia (1); adenocarcinoma (1); adenoma (1); anaphylactic shock (1); angioedema (1); asthma (1); bacterial infection (1); bladder cancer (1); cardiovascular diseases (1); central obesity (1); cholesteatoma (1); chronic myeloid leukemia (1); colorectal tumors (1); dentatorubral-pallidoluysian atrophy (1).
A further 37 diseases each share a sentence with PLCG1 in 1 paper.